CYP1A2 (cytochrome P450 family 1 subfamily A member 2)
Diseases named in the same sentence as CYP1A2 in open-access papers (continued):
Sharing a sentence is not in itself a finding about the gene and the disease.
steatosis (9 papers, 2018 to 2024). Increased lipid within the cytoplasm of cells. "The expression and function of Cyp1a2 are diminished in cases of inflammation and cholestasis, which are both linked to the development of steatosis and cholestasis." (PMID 37881184, 2023). "The objective of our work was to study the impact of periportal steatosis on pericentral drug metabolism focusing on the important CYP isoforms CYP1A2, CYP2D6, CYP2E1, and CYP3A4." (PMID 36528753, 2022). "Based on these observations, caffeine metabolism reflecting the activity of CYP1A2 seems to be affected strongly by the pattern of steatosis with opposing effects." (PMID 36528753, 2022). "The severity of steatosis affected ex-vivo activity of CYP1A2 and CYP2E1." (PMID 36528753, 2022). "Likewise, we can state that the expression pattern of CYP1A2 was similar in all three groups, whereas the activity was negatively correlated to the severity of steatosis reaching moderate significance when comparing severely steatotic with control samples." (PMID 36528753, 2022). "Of note, increased CYP1A2 mRNA expression was lesser in the presence of steatosis." (PMID 29654281, 2018). "On the other hand, two genes (CYP1A2 and FMO1) were downregulated in hepatotoxicity pathway, two genes (SREBF1 and FASN) in steatosis, one each in necrosis (IPO4) and phospholipidosis (SLC2A3) pathways." (PMID 38992651, 2024). "Accordingly, CYP1A2 mRNA expression and enzyme activity are shown to decrease along with NAFLD progression from steatosis to NASH." (PMID 36715540, 2023). "Periportal steatosis did also affect the pharmacokinetics of caffeine (CYP1A2) and midazolam (CYP3A4), but not of codeine (CYP2D6)." (PMID 36528753, 2022). "Regarding more specifically B[a]P metabolism, it is worth noting that neither CYP1A1 nor CYP1B1 mRNA expressions were affected by steatosis alone, in contrast to CYP1A2 whose expression was reduced." (PMID 29654281, 2018).
Parkinson disease (8 papers, 2012 to 2026). A progressive degenerative disorder of the central nervous system characterized by loss of dopamine producing neurons in the substantia nigra and the presence of Lewy bodies in the substantia nigra and locus coeruleus. "CAF interacts with specific genetic variants such as MAPT, SLC2A13, LRRK2, ApoE, NOS2A, GRIN2A, CYP1A2, and ADORA2A, which may influence the risk of developing Parkinson’s Disease (PD)." (PMID 40650030, 2025). "Rasagiline, a drug for Parkinson’s disease is metabolized by CYP1A2 enzyme." (PMID 35480532, 2022).
liver cancer (7 papers, 2016 to 2025). An epithelial or non-epithelial malignant neoplasm that arises from the liver. "The level of AHR is reportedly significantly elevated in various forms of cancer, including breast, ovarian, and liver cancers, and the AHR target genes of CYP1A1 and CYP1A2 are also linked to prognosis." (PMID 34373448, 2021). "We have noted that different liver cancer cell lines responded differently to E2 treatment, hence we examined the expression levels of CYP1A2 and COMT in these cell lines but didn’t get meaningful results to explain the phenomena." (PMID 27093553, 2016). "The highest induction observed in liver cancer cells is also consistent with the specificity of CYP1A2 expression in hepatocytes." (PMID 27093553, 2016). "Furthermore, survival analysis indicated that the expression levels of CYP1A2, ESR1, and AURKA are significantly associated with the prognosis of liver cancer patients, providing potential biomarkers for clinical treatment." (PMID 40864066, 2025). "Moreover, it will be very interesting to further investigate how the HDACs may mediate the regulation on CYP1A2 expression in cancer cells, especially in liver cancer cells." (PMID 27093553, 2016). "We found that CYP1A2 promoter activity was greatly induced by HDAC inhibitors in various cancer cells, especially in liver cancer cells." (PMID 27093553, 2016). "In addition, HDAC inhibitors greatly induced CYP1A2 promoter activities in cancer cells, especially liver cancer cells, but not in non-tumorigenic cells." (PMID 27093553, 2016).
Anxiety (6 papers, 2014 to 2023). Intense feelings of nervousness, tension, or panic often arise in response to interpersonal stresses. "The aim of this study was to assess the influence of the CYP2D6 and CYP1A2 gene polymorphisms on the efficacy of duloxetine treatment in reducing depressive and anxiety symptoms among patients with MDD." (PMID 37686266, 2023). "Specifically, the present study aimed to assess the influence of the CYP2D6 and CYP1A2 gene polymorphisms on the effectiveness of duloxetine in reducing depressive and anxiety symptoms among patients with MDD." (PMID 37686266, 2023). "This study aimed to investigate the influence of the CYP2D6 and CYP1A2 gene polymorphisms on the efficacy of duloxetine in reducing depressive and anxiety symptoms." (PMID 37686266, 2023). "Physical performance may be differentially affected by caffeine depending on CYP1A2 genotype, whereas anxiety and sleep disturbance have been associated with the ADORA2A gene." (PMID 36014860, 2022). "CYP1A2 is responsible for the majority of the metabolism of caffeine, and ADORA2A has been linked to caffeine-induced anxiety." (PMID 30248915, 2018). "The CYP1A2 DMI did not have a significant impact on the reduction in anxiety and depressive symptoms." (PMID 37686266, 2023). "All CaffEQ-BR factors, for the full and brief versions, were ICCs > 0.75, except for factor 6 (anxiety/negative effects; ICC = 0.60), and presented ROC curve values from 0.464 to 0.624 and 0.443 to 0.575 for CYP1A2 and ADORA2A." (PMID 36014860, 2022).
epilepsy (6 papers, 2014 to 2023). A brain disorder characterized by episodes of abnormally increased neuronal discharge resulting in transient episodes of sensory or motor neurological dysfunction, or psychic dysfunction. "Noteworthy, CYP1A2 is largely involved in antipsychotics' metabolism, and we found a CYP1A2*1F/*1F genotype in a patient with bipolar disorder (#13), who could be at increased risk of inadequate response to antipsychotics, potentially improving the management of epilepsy comorbidities." (PMID 36840436, 2023). "Genetic variation in ASMT and another enzyme in the melatonin pathway, cytochrome P450 1A2 (CYP1A2), were identified in children with ASD and epilepsy and comorbid sleep onset delay." (PMID 37998056, 2023).
liver disease (6 papers, 2016 to 2023). "The protein quantitative data are supported by clinical findings, which revealed an altered caffeine (CYP1A2 substrate) pharmacokinetics in liver diseases." (PMID 34575411, 2021). "Its content and activity have been described to be highly influenced by various hepatic diseases and several studies could demonstrate a progressive CYP1A2 decrease following experimental bile duct ligation in mouse and rat models." (PMID 36768808, 2023). "This study demonstrated that CYP1A2, CYP2C19, CYP2D6, and CYP2E1 enzyme activity was differentially affected by the presence of liver disease." (PMID 36901973, 2023). "The present study demonstrates a significant decline of CYP1A2 and CYP2C9 abundances in the course of progression of liver disease, and similar trend is observed for UGT2B15)." (PMID 34575411, 2021). "Activities of CYP2E1, CYP2D6, CYP1A2 and CYP2C19 were all found to decrease with increasing hepatic disease severity, their activities were differentially affected." (PMID 27754327, 2016). "Other authors showed that cancer has no impact on CYP1A2 metabolic activity as compared to liver disease or infection." (PMID 34867341, 2021). "In contrast, CYP1A2 activity was found to decrease linearly with decreasing liver functions and metabolism of mephenytoin by CYP2C19 was already severely impaired by 63% in patients with mild liver disease (Pugh score 5 or 6)." (PMID 27754327, 2016). "Consequently, these combined findings indicate that starting doses of CYP2D6, CYP2E1 and CYP3A4 substrates should be adjusted in patients with moderate or severe liver disease, whereas a dose reduction of CYP2C19 and CYP1A2 substrates should already be considered in milder forms of liver disease." (PMID 27754327, 2016).
liver failure (6 papers, 2013 to 2024). A liver disease characterized by the liver losing or has lost all of its function. "The published clinical pharmacokinetic studies suggest that liver failure can affect CYP1A2, CYP2C19, CYP2D6, CYP2E1 and CYP3A4 activities." (PMID 34575411, 2021). "Notably, as ramelteon is metabolized by the CYP1A2 and CYP2C9 isoforms of cytochrome P450, the drug should not be used in combination with inhibitors of CYP1A2 (i.e., ciprofloxacin) or CYP2C9 (i.e., fluconazole), and it should be administered with caution in patients with hepatic insufficiency." (PMID 36675363, 2023).
prostate carcinoma (6 papers, 2014 to 2021). A carcinoma that arises from epithelial cells of the prostate gland. "The purpose of this study was to determine the impact of HAA intake and genetic polymorphisms in NAT2, CYP1A1, and CYP1A2 on prostate cancer in Japanese men." (PMID 29165164, 2017). "In addition, we found that the NAT2 slow acetylator phenotype, the CYP1A1 GA + GG genotype, and the CYP1A2 CA + AA genotype were associated with increased prostate cancer risk." (PMID 29165164, 2017). "It is unclear how reduced CYP1A2 activity contributes to an increased risk of prostate cancer." (PMID 29165164, 2017). "The purpose of our study was to determine whether there was evidence of an association between HAA intake, polymorphisms in NAT2, CYP1A1, and CYP1A2 and prostate cancer risk in Japanese men." (PMID 29165164, 2017). "High HAA intake was associated with an increased risk of prostate cancer among each genotype and NAT-imputed phenotype, with the exception of the CYP1A2 CC genotype (OR, 2.65; 95% CI, 0.97–7.29; P for interaction, 0.003)." (PMID 29165164, 2017). "Among four case-control studies in Japan, one study each for colorectal, stomach, and prostate cancer investigated whether NAT2 acetylation genotype and CYP1A1 and CYP1A2 genotype modify the association between dietary HAA intake and risk of cancer." (PMID 34315542, 2021). "The increased risk of prostate cancer was observed among individuals with the NAT2 slow acetylator phenotype (OR, 1.65; 95% CI, 1.04–2.61), CYP1A1 GA + GG genotype (OR, 1.27; 95% CI, 1.02–1.59), and CYP1A2 CA + AA genotype (OR, 1.43; 95% CI, 1.03–2.00)." (PMID 29165164, 2017). "A previous study showed that the CYP1A2 CC genotype may be associated with risk of prostate cancer but the finding was not statistically significant." (PMID 29165164, 2017).
ovarian carcinoma (5 papers, 2016 to 2025). A malignant neoplasm originating from the surface ovarian epithelium. "In contrast, the A allele of the CYP1A2*1F genetic variant was found to decrease the risk of ovarian cancer." (PMID 38001897, 2023). "According to the study of Goodman and coworkers, ovarian cancer risk may be modified by CYP1A2 genotype (higher risk among women with the A/A genotype than among women with the C allele) and other factors that influence CYP1A2 expression." (PMID 41516250, 2025). "Moreover, a positive association of CYP1A2 genetic variants with ovarian cancer risk was detected in patients who were tobacco smokers or coffee drinkers." (PMID 38001897, 2023). "No relevant associations of CYP1A2 genetic variants with ovarian cancer risk were found in non-smokers or non-coffee drinkers." (PMID 38001897, 2023). "Moreover, a meta-analysis of 46 case–control studies indicated that CYP1A2*1F polymorphism was associated with estrogen-related breast and ovarian cancer risk, but not lung, colorectal, bladder, endometrial, pancreatic and gastric cancer." (PMID 28418906, 2017).
chronic kidney disease (4 papers, 2020 to 2025). Impairment of the renal function secondary to chronic kidney damage persisting for three or more months. "Poor CYP expression was expected in leukocytes of patients with end-stage renal disease; however, the expression of CYP1A2, CYP2C9, CYP2C19 and CYP3A4 was efficiently quantified using the refined method." (PMID 32638224, 2020). "On the other hand, advanced oxidation protein products that formed due to the ROS attack on proteins down-regulated the expression of CYP1A2 and CYP3A4 in the kidneys of rats’ models for chronic kidney disease." (PMID 34564652, 2021). "The expression of CYP1A2, CYP2C9, CYP2C19 and CYP3A4 was determined in leukocytes of 105 patients with end-stage renal disease and 110 healthy organ donors." (PMID 32638224, 2020). "Comparing organ donors and the patients with end-stage renal disease, significant differences were observed in the proportion of subjects expressed CYP mRNA at low, normal and high levels (Chi2 for CYP1A2: 40.2, for CYP2C9: 87.9, for CYP2C19: 47.2, for CYP3A4: 29.9; df = 2, p < 0.0001)." (PMID 32638224, 2020). "Second, although direct evidence has previously been provided for the correlation between leukocyte expression and hepatic enzyme activities (as well as hepatic expression) of CYP1A2, CYP2C9, CYP2C19 and CYP3A4, it should be validated for patients with end-stage renal disease." (PMID 32638224, 2020).
COVID-19 (4 papers, 2022 to 2025). A disease caused by infection with severe acute respiratory syndrome coronavirus 2. "CYP1A2 showed a decrease of 53% during SARS-CoV-2 infection measured in blood samples from 18 COVID-19 patients, with an inverse correlation with interleukin 6 and C-reactive protein levels." (PMID 36052135, 2022). "CYP1A2, CYP2D6, and CYP2C19 metabolize fluvoxamine and its therapeutic concentrations could be significantly impacted by varying miR-155 levels, which differ between young, healthy individuals and older individuals with co-morbidities in COVID-19." (PMID 38862591, 2024).
Hepatic steatosis (4 papers, 2012 to 2024). Steatosis is a term used to denote lipid accumulation within hepatocytes. "Synthetic inulin ameliorated the change in the expression of CYP1A1 and CYP1A2 in rats fed the HF diet, in association with a suppression of the development of hepatic steatosis." (PMID 22452877, 2012). "Conversely, CYP1A2 expression showed an alcohol concentration-dependent increase, consistent with previous findings suggesting that abnormal lipid metabolism induces hepatic steatosis." (PMID 39120332, 2024). "Our findings also suggest that CYP1A2 plays a more critical role than CYP2E1 in acute alcohol-induced fatty liver disease." (PMID 39120332, 2024). "According to the previous study, a 44% decrease in the activation of CYP1A2 was detected in the liver cells of a fatty liver disease patient compared with the controls." (PMID 28671602, 2017). "Therefore, the down-regulation of CYP1A2 after RIF administration in the mouse model in this study might be related to fatty liver disease." (PMID 28671602, 2017).
insomnia (4 papers, 2020 to 2025). A sleep disorder characterized by difficulty in falling asleep and/or remaining asleep. "Another association was found between CYP1A2 NM/RM (normal metabolizers/rapid metabolizers) phenotype vs. UM (ultrarapid metabolizers) and reports of insomnia during aripiprazole administration." (PMID 36873203, 2023). "Of note, C-allele carriers in the CYP1A2 gene showed higher ratings of insomnia, and thus should evaluate the use of caffeine to increase their performance in evening training sessions as they may experience a higher frequency of insomnia when using this supplementation strategy." (PMID 32823594, 2020). "The use of caffeine to increase performance in team-sports should be evaluated compared to its side-effects, especially in CYP1A2 C-allele carriers and ADORA2A TT homozygotes as insomnia, diuresis, and excessive activeness may be reported by athletes with these genotypes." (PMID 32823594, 2020).
nonalcoholic fatty liver disease (4 papers, 2012 to 2025). "Decrease in hepatic CYP1A2 content has been reported previously in other liver pathologies, i.e. non-alcoholic fatty liver disease (NAFLD), and at mRNA level—in alcoholic liver disease (ALD), primary sclerosing cholangitis (PSC) and hepatitis C virus (HCV)-induced liver damage." (PMID 34117631, 2021). "Likewise, nonalcoholic fatty liver disease (NAFLD) was associated with decreased mRNA, protein amount, and functional activity of microsomal CYP1A2 compared to healthy liver tissue." (PMID 33322313, 2020).
alcoholic liver diseases (3 papers, 2021 to 2024). A disorder caused by damage to the liver parenchyma due to alcohol consumption. "Alcoholic liver disease and primary biliary cholangitis were involved in the most prominent changes in the protein abundances, with downregulation of 6 (CYP1A2, CYP2C8, CYP2D6, CYP2E1, CYP3A4, UGT2B7) and 5 (CYP1A1, CYP2B6, CYP2C8, CYP2E1, CYP3A4) significantly downregulated enzymes, respectively." (PMID 34575411, 2021).
Alzheimer disease (3 papers, 2014 to 2025). A progressive, neurodegenerative disease characterized by loss of function and death of nerve cells in several areas of the brain leading to loss of cognitive function such as memory and language. "Thus, the upregulation of miR-122 and/or miR-132-5p may be associated with decreased activity of CYP1A2 at the transcript, protein, and enzyme activity levels, which could have therapeutic potential in Alzheimer's disease." (PMID 39812050, 2025). "In short, CYP1A2 seems to be upregulated in Alzheimer's disease." (PMID 39812050, 2025). "Reduced exosomal expression of miR-122 in the blood of Alzheimer's disease patients may lead to the derepression of CYP1A2." (PMID 39812050, 2025). "This hypothesis is supported by reports showing that caffeine, which is metabolized primarily by CYP1A2, can significantly protect against or reverse AD-like cognitive impairment and Aβ neuropathology in Alzheimer's disease mouse models." (PMID 39812050, 2025).
asthma (3 papers, 2013 to 2025). "A study examining CYP1A2 gene polymorphisms found that patients with asthma and COPD who carried specific alleles exhibited significantly reduced theophylline clearance." (PMID 40149465, 2025). "The sex discrepancy was also reported in a previous study showing that coffee consumption was inversely associated with asthma in women but not in men, which might be explained by the faster caffeine clearance in males than females due to the inhibited CYP1A2 activity by estradiol." (PMID 36235690, 2022).